CDC25A (cell division cycle 25A)
Description:
Tyrosine protein phosphatase which functions as a dosage-dependent inducer of mitotic progression. Directly dephosphorylates CDK1 and stimulates its kinase activity. Also dephosphorylates CDK2 in complex with cyclin-E, in vitro.
Synonyms: CDC25A2
Tractability: Small molecule: a high-quality ligand is known; it belongs to a druggable protein family. PROTAC: UniProt records ubiquitination sites on it; ubiquitination databases record sites on it; a small molecule that binds it is known.
Target class: Phosphatase; Serine/threonine/tyrosine protein phosphatase; Enzyme; Protein Phosphatase
Gene: Protein-coding gene on chromosome 3 (48,157,146 to 48,188,417, reverse strand). Ensembl gene ENSG00000164045.
Subcellular location (Human Protein Atlas): Nucleoplasm; Golgi apparatus
Pathways (Reactome):
Cell Cycle: Activation of ATR in response to replication stress; Cyclin A/B1/B2 associated events during G2/M transition; Cyclin A:Cdk2-associated events at S phase entry; Cyclin E associated events during G1/S transition; G1/S-Specific Transcription; Polo-like kinase mediated events; Transcription of E2F targets under negative control by DREAM complex; Ubiquitin-Mediated Degradation of Phosphorylated Cdc25A
Disease: Deregulated CDK5 triggers multiple neurodegenerative pathways in Alzheimer's disease models
Metabolism of proteins: Ub-specific processing proteases
Gene Ontology:
Molecular function: phosphoprotein phosphatase activity; protein binding; protein kinase binding; protein tyrosine phosphatase activity; protein-folding chaperone binding
Biological process: G2/M transition of mitotic cell cycle; positive regulation of G2/M transition of mitotic cell cycle; response to radiation; cell population proliferation; G1/S transition of mitotic cell cycle; positive regulation of DNA replication; positive regulation of G2/MI transition of meiotic cell cycle; regulation of cyclin-dependent protein serine/threonine kinase activity; positive regulation of cell cycle G2/M phase transition
Cellular component: cytoplasm; cytosol; nucleoplasm; nucleus
Genetic constraint (gnomAD): Loss-of-function variants: 10 observed, 34.72 expected, observed/expected ratio (o/e) 0.29, 90% interval 0.18 to 0.49. The upper end of that interval is the gene's LOEUF score, 0.49, which puts it in group 2 of 6, group 1 being the genes least tolerant of losing a copy. Missense variants: 331 observed, 465.94 expected, observed/expected ratio (o/e) 0.71, 90% interval 0.65 to 0.78. Synonymous variants: 170 observed, 172.18 expected, observed/expected ratio (o/e) 0.99, 90% interval 0.87 to 1.12.
Homologues: Orthologues: chimpanzee CDC25A (99% identical), macaque CDC25A (98% identical), dog CDC25A (92% identical), pig CDC25A (91% identical), rat Cdc25a (86% identical), mouse Cdc25a (85% identical), guinea pig CDC25A (84% identical), rabbit CDC25A (77% identical), zebrafish cdc25b (49% identical), Drosophila melanogaster stg (25% identical), Drosophila melanogaster twe (23% identical), Caenorhabditis elegans cdc-25.2 (20% identical), and 2 more. Paralogues in human: CDC25B (48% identical), CDC25C (32% identical).
Diseases named in the same sentence as CDC25A in open-access papers:
CDC25A is named in the same sentence as 120 diseases in open-access papers, as found by Europe PMC text mining. Sharing a sentence is not in itself a finding about the gene and the disease. The quoted sentences say what the papers report.
breast carcinoma (53 papers, 2002 to 2025). "CDC25A dysregulation, however, has been linked to a number of malignancies, including breast cancer." (PMID 38606093, 2024). "Many reports showed that Cdc25A and Cdc25B were associated with breast cancers, colorectal cancers, non-small cell lung cancers and so on." (PMID 37468905, 2023). "High levels of Klhl24, Hbp1, Crebrf, Ypel2, CD22 and Ypel3 were correlated with better outcomes, whereas lower levels of Gdf15, Cdc25a, Ddit4 and Psat1 were associated with better prognosis in breast cancer patients." (PMID 34990474, 2022). "In contrast, lower levels of the mRNAs for Gdf15, Cdc25a, Ddit4 and Psat1 were associated with better prognosis in breast cancer patients." (PMID 34990474, 2022). "CDC25A is overexpressed in many tumor cells and is associated with the malignancy and prognosis of several cancers, such as human glioma, retinoblastoma, breast cancer, and liver cancer." (PMID 32528520, 2020). "Importantly, we found higher expression of CDC25A in BRCA1/2-deficient tumors in different breast cancer data sets." (PMID 29416040, 2018). "Furthermore, overexpression of CDC25A in small breast carcinomas is associated with poor survival in patients." (PMID 23809258, 2013). "Overexpression of CDC25A is associated with poor prognosis in breast cancers." (PMID 18786252, 2008). "Similarly, CDC25A phosphatase has been implicated in replication stress and breast cancer." (PMID 39237765, 2024). "CDC25A is crucial for cell cycle progression, but its overactivity in breast cancer drives uncontrolled growth by over-activating CDKs." (PMID 40081286, 2025). "MiR‐99a‐5p down‐regulates CDC25A to inhibit breast cancer progression and can serve as a biomarker for hepatocellular carcinoma." (PMID 39548655, 2024). "In breast cancer cell lines (MCF-7 and MDA-MB-231), miR-99a-5p significantly inhibited the proliferation and invasion of breast cancer cells and promoted apoptosis by targeting CDC25A and inhibiting its expression in cells." (PMID 37081566, 2023). "For instance, downregulation of CDC25A reduced proliferation and cell cycle progression of liver cancer cells, breast cancer cells, and so forth." (PMID 34266408, 2021). "It has been reported that DUB3 removes the polyubiquitin modification of CDC25A, which prevents its degradation, thus amplifying the oncogenic role of CDC25A in breast cancer." (PMID 34454495, 2021). "CDC25A is of particular interest since miR-21 was already previously shown to restrain carcinogenesis in colon and breast cancer, in part by repressing the expression of CDC25A." (PMID 34638467, 2021). "CDC25A overexpression had been found in breast cancer and CDC6 overexpression in cervix, lung and brain cancer." (PMID 32817744, 2020). "A second study revealed that Cdc25A was overexpressed in 47% of breast cancer cases, in a cohort of 144 patients." (PMID 32964114, 2020). "Considered an oncogene, CDC25A is highly expressed in many types of human malignancies, such as breast cancer, ovarian cancer, head and neck cancer, colon cancer, and cutaneous squamous cell carcinoma." (PMID 33282948, 2020). "Previously, the deregulation of CDC25A protein has been correlated with increased expression of ubiquitin hydrolase DUB3 in breast cancer cell lines or dysfunction of β-TRCP in lung cancer." (PMID 29416040, 2018). "In summary, here we have shown that treatment with CPX induced the phosphorylation of Cdc25A, which promoted the protein degradation of Cdc25A in rhabdomyosarcoma (Rh30) and breast cancer (MDA-MB-231) cells." (PMID 28680535, 2017). "Meanwhile, DIM inhibited breast cancer cell proliferation and induced cell cycle arrest in G2/M phase in MCF-7 breast cancer cells, via enhancing miR-21-mediated Cdc25A degradation." (PMID 28698459, 2017). "Our results indicated that CPX induced the phosphorylation of Cdc25A, which promoted protein degradation of Cdc25A in rhabdomyosarcoma (Rh30) and breast cancer (MDA-MB-231) cells." (PMID 28680535, 2017).
breast carcinoma (continued). "In breast cancer, cell division cycle 25A (CDC25A) mediates metastasis by regulating MMP1 through FOXO1." (PMID 27486383, 2016). "Additionally, the overexpression of CDC25A, B and C were found in many cancer types, e.g., lung cancer, breast cancer and liver cancer." (PMID 40731028, 2025). "Cell cycle regulators Wee1, CDC25A/B and Emi-1 are other known βTrCP substrates which play an oncogenic role, specifically the overexpression and up-regulation of CDC25A/B and Emi-1 has been accounted for in human tumour cell lines and cancers such as ovarian, colorectal and breast cancers." (PMID 37293994, 2023). "Overexpression of miRNA-99a and decreased expression of CDC25A could suppress breast cancer cell proliferation and invasion." (PMID 32403384, 2020). "In addition, CDC25A promotes breast cancer cell growth in mouse models." (PMID 34123834, 2021). "CDC25A is of particular interest since it is a well-characterized oncogene promoting cell cycle progression in cancer cells and because miR-21 was already previously shown to restrain carcinogenesis in colon and breast cancer, in part by repressing the expression of this specific oncogene." (PMID 34638467, 2021). "MiR‐99a‐5p by downregulating CDC25A could suppress breast cancer progression and G1/S transition." (PMID 33330110, 2020). "Importantly, high expression of Dub3 in mouse embryonic stem cells (ESCs) couples the G1/S checkpoint with pluripotency through Cdc25A de-ubiquitination, and Dub3 depletion reduces the proliferative potential of breast cancer cells in vivo by degradation of Cdc25A." (PMID 29088851, 2017). "In luminal (ER+) breast carcinoma (BC), miRNA profiling identified miR‐195‐5p as a key regulator of proliferation that targets CHEK1, CDC25A, and CCNE1." (PMID 40548926, 2025). "We examined the expression levels and clinical relevance of CHEK1, CDC25A, CCNE1, hsa‐miR‐195‐5p, and hsa‐miR‐497‐5p in a comprehensive cohort of 217 breast carcinoma patients." (PMID 40548926, 2025). "This study enhances breast cancer research by revealing Episesamin's ability to specifically target and downregulate key cell cycle genes CDK1, CDC25A, and PLK1." (PMID 40081286, 2025). "The multivariate logistics regression analysis was applied to evaluate the performance of the panel of 3 genes (CDK1,CDC25A and PLK1) as biomarkers for breast cancer prediction." (PMID 40081286, 2025). "Episesamin, a major phytoconstituent of C. urens, was found to target CDK1, CDC25A, and PLK1-key cell cycle regulators in breast cancer." (PMID 40081286, 2025). "The bioinformatics analysis identified CDK1, CDC25A, and PLK1 as pivotal genes regulating cell cycle progression and breast cancer tumorigenesis." (PMID 40081286, 2025). "Targeting multiple genes, such as CDK1, CDC25A, and PLK1, effectively induces cell cycle arrest, offering a promising therapeutic strategy for breast cancer." (PMID 40081286, 2025). "The study focuses on exploring the therapeutic potential of Caryota urens fruit against breast cancer, specifically targeting cell cycle genes CDK1, CDC25A, and PLK1 through bioinformatics, network pharmacology, and in vitro validation." (PMID 40081286, 2025). "There are two mRNA genes specified in this network (CDC25A and BIRC5) whose expression significantly correlated with upregulated miRNAs, namely hsa-mir-100 and hsa-mir-218-2, which are also known to be breast cancer drug targets." (PMID 40724805, 2025). "Targeting CDK1, CDC25A, and PLK1 offers a promising therapeutic strategy in breast cancer due to their pivotal roles in cell cycle regulation." (PMID 40081286, 2025). "Both CDC25A and PLK1 serve as potential therapeutic targets and biomarkers, offering promise for personalized breast cancer treatments by halting uncontrolled cell growth." (PMID 40081286, 2025).
breast carcinoma (continued). "Based on various bioinformatics, in silico docking and in vitro MCF7 cell line study reveals that the C. urens fruit extract targets the genes of cell cycle i.e. CDK1,CDC25A, and PLK1 in breast cancer." (PMID 40081286, 2025). "Another study showed that Ciclopirox inhibits the proliferation of cancer cell lines including MCF7 breast cancer cells, A549 lung cancer cells, and HT29 colon cancer cells via suppressing Cdc25A." (PMID 39773231, 2025). "Thus, CDC25A might serve as a potential therapeutic target in breast cancer." (PMID 38606093, 2024). "One of the compounds that has an inhibitory effect towards CDC25A/B is an o-hydroxybenzyl derivative RE44 (10d), which has shown promise in models of mouse tsFT210 breast cancer cell line in vivo." (PMID 38606093, 2024). "MiR-99a inhibited breast cancer tumorigenesis and progression by targeting the mTOR/p-4E-BP1/p-S6K1 pathway and the cell-cycle pathway through downregulating CDC25A." (PMID 37508580, 2023). "For example, cell division cycle 25A (CDC25A) directly regulates the transcription of matrix metalloproteinase 1 through FOXO1, thereby enhancing the invasive ability of breast cancer cells." (PMID 34123834, 2021). "Previous studies suggest that Cdc25A can increase Foxo1 stability, while Foxo1 can enhance transcription of MMP1, leading to enhanced breast cancer cell metastasis." (PMID 28334049, 2017). "Leveraging bioinformatics tools and experimental validation, the research explores the interactions between C. urens components and key genes, including CDK1, CDC25A, and PLK1, which are crucial for cell cycle regulation and often dysregulated in breast cancer." (PMID 40081286, 2025). "In the present study the treatmnet of MCF7 cell treated with the CU (200–500 μL) fraction for 24 h and significantly down regulation of the CDK1, CDC25A and PLK1 which is involved in cell cycle, and responsible for cell cycle arrest in tumour cells of breast cancer." (PMID 40081286, 2025). "Meanwhile, previous studies speculated that CDC25A was one of the direct transcriptional regulatory target genes of NPAS2, which was confirmed in breast cancer and hepatocellular carcinoma." (PMID 40548841, 2025). "Both evaluated miRNAs exhibited significant downregulation in breast carcinomas compared to adjacent mammary tissues and, in contrast, the expression of CHEK1, CDC25A and CCNE1 genes was significantly increased in malignant versus adjacent tissues (N = 18, P < 0.01 for all)." (PMID 40548926, 2025). "Further analysis demonstrated that the expression of cell cycle-related genes (CDC6, CDC25A, CDK1, ATM, E2F1, and MKI67) were much higher in breast cancer patients of 3 target genes high expression group or MIR3613 deletion group compared with their counterpart, respectively." (PMID 33494814, 2021). "We next analyzed the relationship between the expression of Cyclin E, c-MYC, Cdc25A, and markers of replication stress with disease-free survival (DFS), recurrence-free survival (RFS) or overall survival (OS) in our breast cancer cohort (n = 379) using Cox regression analyses." (PMID 32964114, 2020). "Besides, seven genes including BRCA1, FN1, CCNE1, CCND1, CHEK1, BUB3, and CDC25A were identified as the hub nodes by the PPI network, and CCNE1 and CHEK1 were confirmed to be related with the prognostic survival of the patients with breast cancer." (PMID 35186236, 2022). "However, neither overexpression of cyclin D1 or of cdc25A was found to be an independent indicator of prognosis in early stage breast cancer." (PMID 11875707, 2002). "CDK1, CDC25A, and PLK1 were upregulated in breast cancer compared to normal tissues, based on BRCA data analysis." (PMID 40081286, 2025). "In conclusion, here we have shown that CPX induced Cdc25A degradation neither by increasing CK1α or decreasing DUB3 expression, nor via activating GSK3β in rhabdomyosarcoma (Rh30) and breast carcinoma (MDA-MB-231) cells." (PMID 29725502, 2018).
breast carcinoma (continued). "Here, we show that CPX induced the degradation of Cdc25A neither by increasing CK1α or decreasing DUB3 expression, nor via activating GSK3β, but through activating Chk1 in rhabdomyosarcoma (Rh30) and breast carcinoma (MDA-MB-231) cells." (PMID 29725502, 2018).
hepatocellular carcinoma (34 papers, 2010 to 2025). A malignant tumor that arises from hepatocytes. "Exclusive overexpression of CDC25A in hepatocellular carcinoma is rare, while pancreatic ductal carcinoma and gastric carcinomas exclusively overexpress Cdc25B (Kristjánsdóttir and Rudolph, 2004)." (PMID 38313315, 2024). "A recent study has shown that upregulated NPAS2 promoted the survival of hepatocellular carcinoma cells through the upregulation of cell division cycle 25 A (CDC25A) and inhibition of mitochondria-dependent intrinsic apoptosis." (PMID 34285836, 2021). "It has been reported in hepatocellular carcinoma that ROCK2 regulates the cell division process by regulation of the ubiquitination of Cdc25A, a G1/S transition protein." (PMID 31488179, 2019). "For example, it is demonstrated that inhibiting CDC25A suppresses the growth of hepatocellular carcinoma cells." (PMID 29515890, 2018). "Additionally, CDC25A contributes to the development of pancreatic cancer, colon cancer, hepatocellular carcinoma, and other cancers." (PMID 38613794, 2024). "Similarly, overexpression of miR-199a-5p inhibited cellular proliferation in hepatocellular carcinoma (HCC) cells by binding to the mRNA of CDC25a to reduce its expression." (PMID 37835506, 2023). "NPAS2 increases liver fibrosis in hepatocellular carcinoma by direct transcriptional activation of Hes1 in hepatic stellate cells and induces glucose metabolism reprogramming and cell survival by transactivating CDC25A in liver cancer cells." (PMID 35880088, 2022). "ROCK2 promotes hepatocellular carcinoma via the ubiquitination of CDC25A." (PMID 34128694, 2021). "Tumor CDC25A expression was strongly associated with metastatic diseases in hepatocellular carcinoma, and PLK1 could be an upstream regulator of CDC25A." (PMID 29246203, 2017). "Elevated expression of NPAS2 in hepatocellular carcinoma (HCC) triggers CDC25A transactivation, dephosphorylates Bcl-2, and ultimately inhibits apoptosis." (PMID 36978001, 2023). "ROCK2 is overexpressed in human hepatocellular carcinoma (HCC) cells, and its inhibition induces ubiquitin-mediated degradation of Cdc25A, which is responsible for cell cycle progression through the S phase via CDK2/Cyclin-E activation." (PMID 33546351, 2021). "In a rat hepatocellular carcinoma model, EGCG inhibited the growth of hepatocellular carcinoma by upregulating P21waf1/Cip and downregulating CDC25A expression." (PMID 40218859, 2025). "In hepatocellular carcinoma, NPAS2 promotes cell survival and proliferation by upregulating phosphatase CDC25A expression through direct binding to the E-box element in the CDC25A promoter." (PMID 40243466, 2025). "CHEK1, CDC25A, and CCNE1, together with CCND1, CCND3, CDK4, CDK6, BTRC, E2F3, and FOXK1, were previously identified as the targets of miR‐497∼195 cluster in hepatocellular carcinoma." (PMID 40548926, 2025). "Several studies have demonstrated that lncRNA SNHG11 serves as a miR-184 sponge in hepatocellular cancer cells, whereas the latter targeted 3′-UTR of CDC25A in non-small cell lung cancer." (PMID 33816469, 2021). "No core clock genes are detected among the top ten 24-h rhythmic candidate genes detected in SW620 cells, but one of the candidate genes, CDC25A, is a target of the core clock protein NPAS2 and known to promote cell survival of hepatocellular carcinoma." (PMID 32295075, 2020). "It reported that has-miR-195-497 cluster was intracellular antagonists of BMP signaling pathway in bone cells in and targeting cell cycle proteins CDK6, CCNE1, CDC25A and CDK4 to regulated cell proliferation in human hepatocellular carcinoma cells." (PMID 27384321, 2016).
hepatocellular carcinoma (continued). "Hepatoma cells (SK-Hep1 and Huh 7) transfected with ISX shRNAi showed significant downregulation of E2F1 and DP1 protein expression as well as of proliferation markers (cyclin D1, c-Myc, Cdc25A, and PCNA) and anti-apoptotic genes (p65 and Mcl-1)." (PMID 27175585, 2016).